APOE (apolipoprotein E)
Diseases named in the same sentence as APOE in open-access papers (continued):
Sharing a sentence is not in itself a finding about the gene and the disease.
dementia (continued). "Human APOE exists as three common alleles (APOE2, APOE3, and APOE4); APOE4 occurs in nearly 25% of the US population, and is the strongest genetic risk factor for dementia associated with neurodegenerative diseases such as AD and Diffuse Lewy Body Disease." (PMID 37944881, 2024). "As expected, the MCI and dementia groups both showed worse performance scores in the neuropsychological tests and higher proportions of APOE ε4 carriers than the NC group (all p < 0.001); the AD CSF core biomarkers were also more altered in these two groups than in the NC group (all p < 0.001)." (PMID 39328245, 2024). "For mild dementia, retained time-varying effects were Aβ1–42, age, APOE ε4, and baseline MMSE." (PMID 38986053, 2024). "Individuals who were homozygous for the APOE ε4 allele were 5.5 to 9.4 times more likely to die with dementia compared with noncarriers for the APOE e4 allele (χ2P < .001) (eTable 1 in Supplement 1)." (PMID 38709531, 2024). "The most prevalent type of dementia, AD, has been intensively examined for the APOE gene." (PMID 38607741, 2024). "People diagnosed with APOE ε4 showed a reduced tendency to consume ginger, decreased internet usage, a higher probability of experiencing sleep issues, and a greater chance of mild cognitive impairment or dementia (p < 0.05)." (PMID 39639910, 2024). "Still, it remains unclear as to how the overall APOE concentration or its particular isoforms relate to Aβ, phosphorylated protein tau levels, the degree of severity of dementia, or other biological parameters." (PMID 39449522, 2024). "Although the APOE ε4 allele did not link directly to PD severity in our study, it was more prevalent in dementia patients." (PMID 38792885, 2024). "We did not observe significant association of metabolite levels with MCI to AD dementia progression in both models with and without APOE adjustment and in APOE stratified analysis." (PMID 39080778, 2024). "Family history of dementia, APOE ε4 carrier status, age (in years), baseline PACC, screening state trait anxiety inventory (STAI), baseline CFI participant and screening geriatric depression scale were all significantly associated with study discontinuation status at 0.1 level of significance." (PMID 39044496, 2024). "The APOE increase in PCOS has been associated with neurodegenerative diseases, such as dementia." (PMID 39457593, 2024). "Patients with pRBD at baseline had a greater risk of dementia compared with those with no pRBD (HR 1.785, 95% CI 1.032–3.087, p = 0.038), while adjusting for age, gender, education, age of onset, and APOE ɛ4 carriers." (PMID 38764318, 2024). "Regarding impulse dyscontrol, some cross-sectional studies have shown that the APOE e4 allele is related to agitated behavior in patients with dementia, although longitudinal evidence has not confirmed these findings." (PMID 38473892, 2024). "apoE is involved in several potentially pathologic processes that may lead to the development of dementia." (PMID 39031528, 2024). "Our results showed that the carrying status of APOE ε4 could change the influence of daily lifestyle on cognitive decline, and the influencing factors of MCI and dementia were significantly different with APOE ε4 gene carrying status." (PMID 39639910, 2024). "Nevertheless, once individuals have reached the Aβ PET+ stage, the elevated risk of dementia is predominantly influenced by their sleep status rather than their APOE genotype." (PMID 38421124, 2024). "The authors present their findings that smoking was associated with a 2.18-fold increased risk of dementia in comparison to nonsmokers; this association was not influenced by APOE genotype." (PMID 38607741, 2024). "Indeed, some evidence suggests that the effect of APOE ε4 on cognitive function and dementia differs across ancestries and race/ethnicities." (PMID 38889280, 2024).
dementia (continued). "Notably, a few genes have come to light as important participants in the genetic architecture of dementia, including the presenilins (PSEN1 and PSEN2), the apolipoprotein E (APOE) gene, and microtubule-associated protein tau (MAPT)." (PMID 38607741, 2024). "However, in this subgroup, higher interleukin-2 soluble receptor (IL-2sr) and apolipoprotein E levels, higher internal carotid IMT, and lower descending aortic strain were also associated with dementia." (PMID 38635767, 2024). "Finally, the proportion of APOE ε4 carriers was much higher among those who later developed dementia, in particular among those who were diagnosed with AD (50.4%), than among participants with no dementia diagnosis (25.0%)." (PMID 39160600, 2024). "This study did not account for APOE ε4 carrier status, although a recent study found that associations between diet and dementia risk were independent of genetic predisposition." (PMID 39270936, 2024). "To date, the vast majority of studies regarding genetic predisposition for dementia in individuals with SCD have compared APOE ε4 carriers with non-carriers." (PMID 38534745, 2024). "Ten patients carried the APOE ε4 allele, with a higher prevalence of dementia compared to those who did not carry the allele (9/10 vs. 32/62, p = 0.036)." (PMID 38792885, 2024). "In a targeted study of over 2000 Swedish individuals over 70 years old, a 39-SNP AD-PRS was associated with incident dementia in individuals who were APOE ε4 non-carriers (HR = 1.22 [1.10–1.35], p = 2 × 10−4)." (PMID 38279230, 2024). "The stratification algorithm we use combines diagnosis of MCI, carriage of the apolipoprotein E (APOE) ε4 allele, family history of dementia in a first-degree relative, advancing age (treated as continuous variable), sex and where available cognitive function and AD biomarkers in plasma." (PMID 38908839, 2024). "Also, the sample size was limited for stratification on APOE, and larger studies are needed to provide more robust evidence regarding the interaction between family history of dementia and APOE genotype." (PMID 39387967, 2024). "A recent prospective study reported that higher concentrations of EPA were associated with a lower incidence of AD and a decreased risk for all-cause dementia and AD among apolipoprotein Eε4 (APOE ε4) noncarriers but not among APOEε4 carriers." (PMID 38396924, 2024). "The kidney function–dementia association remained significant after stratification by diabetes status (yes vs no), hypertension status (yes vs no), and APOE genotype (ε4 allele carriers vs noncarriers)." (PMID 37578935, 2024). "In the sensitivity analyses, the association between playing computer games and dementia remained significant after further adjusting for baseline frailty status, social isolation, depressive symptoms, medication burden, family history of dementia, and APOE ε4 carrier." (PMID 38898507, 2024). "Genetic predisposition (apolipoprotein E) appeared among top correlates of dementia in older adults but not for the entire cohort." (PMID 38635767, 2024). "Plasma biomarkers, Aβ PET, tau PET, hippocampal volume, and temporal-metaROI cortical thickness were compared between normal control (NC), subjective cognitive decline (SCD), mild cognitive impairment (MCI), and dementia groups, controlling for age, sex, and APOE-ε4." (PMID 38627753, 2024). "The impact of tau on cognition is also dramatically illustrated in an AD individual homozygous for the Christchurch mutation in APOE, which presented low levels of tauopathy and absence of dementia even when displaying an advanced brain amyloidosis." (PMID 39707506, 2024). "We further identified that the majority of shared metabolomic markers predicted dementia risk, and further adjustment for the APOE e4 genotype did not substantially alter these associations." (PMID 38829458, 2024).
dementia (continued). "Even though HR point estimates of increased risk generally favored APOE ε4 carriers, confidence intervals were large, leading us to conclude that carriage of at least one APOE ε4 allele did not alter risk for dementia in the context of abnormal domain scores." (PMID 38877664, 2024). "Other genetic variables contribute to the complex landscape of dementia in addition to APOE." (PMID 38607741, 2024). "Notably, while the main effect of lifelong composite CR on cognitive transitions was most apparent during the predementia stages, the potential interaction of CR and APOE‐ε4 status was most visible for transitions from normal cognition to dementia." (PMID 38779828, 2024). "None of the Dementia subjects in Cluster 3 showed the highest risk genotype for APOE (E4/E4), a difference that obtained a significant p-value (0.0322)." (PMID 38693203, 2024). "Through effects on neuroinflammation and blood brain barrier integrity APOE-ε4 carriership is an important risk factor for AD and non-AD related dementias." (PMID 39415269, 2024). "Not all people carrying the APOE ε4 allele develop AD or dementia, whereas some people without the APOE ε4 allele do." (PMID 38792885, 2024). "HSV did not appear to interact with CMV or APOE ɛ4 carriage in association with AD or dementia, but further studies with more power are needed to examine such potential interactions." (PMID 38306033, 2024). "In this line, in a recent study based on the clinical and neuropathological records of the National Alzheimer’s Coordinating Center (NACC) in the United States, the results supported that Apolipoprotein E (APOE) genotype, a strong genetic factor for AD, modifies the obesity paradox in dementia." (PMID 39273736, 2024). "On the contrary, the contribution of the MBI domains of apathy and affective dysregulation on dementia risk seems to be stronger among APOE e4 non-carriers." (PMID 38473892, 2024). "In the SNAC‐K total sample, using the Markov multistate survival model, a marginally statistically significant interaction was observed between composite CR score and APOE genotypes on the transition from normal cognition to dementia (P for interaction = 0.051)." (PMID 38779828, 2024). "Among 10 individuals with the APOE ε4 gene, the prevalence of dementia was higher than those without the ε4 allele (9/10 vs. 32/62, p = 0.036)." (PMID 38792885, 2024). "High education may buffer the effect of APOE ε4 on the clinical manifestation of dementia by enhancing cognitive reserve." (PMID 38792885, 2024). "Therefore, large‐scale epidemiological studies employing nationally representative data are needed to comprehensively explore the effects of APOE ε4 on cognition and dementia and identify potential effect modifiers in Indian/South Asian populations." (PMID 38889280, 2024). "We observed an interaction with this genotype, with strong associations between multinutrient suboptimal statuses and dementia in carriers, but not in non‐carriers of the APOE ε4 allele." (PMID 38865433, 2024). "It is possible that this reflects a difference in GABAergic inhibitory neuronal function, especially given the association between APOE −e4 and subclinical epileptiform activity that can occur in patients without dementia when experiencing stress." (PMID 39632090, 2024). "Another meta-analysis showed that APOE ε2+ was neither a risk factor nor a prevention factor for Parkinson’s disease dementia (PDD), while APOE ε4+ was a risk factor for PDD." (PMID 39639910, 2024). "Maternal family history of AD and dementia was strongly and consistently associated with all five EPAD subgroups, with memory subgroup showing the strongest association (p=3.3e-16), which is consistent with the higher frequency of APOE ε4 in this subgroup." (PMID 38787369, 2024). "Polymorphisms in the apolipoprotein E gene, APOE, associated with both infectious disease susceptibility and dementia risk, could play a role." (PMID 38271405, 2024).
dementia (continued). "In a preliminary analysis, BBB permeability was associated with dementia and vascular risk factors but not amyloid pathology or APOE genotype." (PMID 37213537, 2023). "Our findings, if confirmed by replications, may have implications for the development of dementia prevention strategies targeting the improvement of handgrip strength training and vitamin D supplementation, especially among individuals with APOE e4 carries." (PMID 37246226, 2023). "Despite this increased risk, there are some APOE ɛ4 carriers who remain cognitively normal and do not go on to develop dementia or cognitive impairment even in very old age4." (PMID 37198167, 2023). "Because APOE ε4 is a cause of dementia, a positive association is thus induced between low education and dementia in the analytic sample, even though there is no causal relationship between them in truth." (PMID 38435670, 2023). "Association between dementia and the combined association of vitamin D/grip strength and APOE ε4 genotype did not meaningfully differ by age, education level, and socioeconomic status (all P for interaction > 0.05)." (PMID 37246226, 2023). "Amongst the strengths of this study were its large sample size of UK Biobank participants, device-based physical activity, prospective design, comprehensive outcome (including dementia and its subtypes) and collection of various potential confounders (such as APOE ε4 carrier status)." (PMID 37198574, 2023). "Therefore, when evaluating potential mechanistic pathways other factors, such APOE genotype and dementia aetiology should also be considered." (PMID 37467176, 2023). "We aimed to investigate the independent and additive relationships of walking pace and handgrip strength on the risk of new-onset dementia and examine the potentially modifying effects of age, APOE phenotypes, lifestyle factors, and family history of dementia in the relationships." (PMID 36624486, 2023). "A subgroup analysis based on APOE ε4 carrier status demonstrated consistent results, with metformin use not correlating with a reduced severe dementia risk." (PMID 38001936, 2023). "In this study, we examined the association among three visual rating scores and dementia severity in APOE e4 carriers and non-carriers." (PMID 36864910, 2023). "A shift from the amyloid hypothesis to genetic causes like the APOE Ɛ4 risk haplotype and variants, e.g., PSEN1 has led to a better understanding of the biology of dementia." (PMID 38028602, 2023). "Half of participants with AD diagnosis, 39% of ACD participants, and 25% of participants without dementia diagnosis throughout follow-up had one or more APOE e4 alleles." (PMID 37516890, 2023). "Among APOE ɛ4 noncarriers, there was a significant risk of dementia with large BMI loss but not large BMI gain." (PMID 35921193, 2023). "In secondary analyses, we found evidence of a statistically significant interaction between eGFRcr-cys status and APOE with risk of incident dementia, but not for age, sex, or non-APOE dementia PRS." (PMID 37605228, 2023). "Effect modification analyses showed that the association between LTL and dementia (including AD and VD) was not modified by APOE ε4 status (p for interaction >0.05)." (PMID 37705928, 2023). "The pattern of LD between APOE Ɛ4 and TOMM40 differs across populations, and the effect of these may together, or independently contribute to the risk of dementia." (PMID 38028602, 2023). "Previous studies reported lower plasma apolipoprotein E (apoE) levels in NHW APOEε4-carriers compared to non-carriers, and low plasma apoE levels were directly associated with an increased risk of AD and all dementia." (PMID 37400888, 2023). "In analyses of participants without APOE ε4 alleles, the results were similar to those in the main analyses for men and women, apart from an unexpected lower dementia risk found for higher TC, LDL‐C, and non‐HDL‐C for ≥20 year follow‐up in men." (PMID 37243914, 2023).
dementia (continued). "More work is needed to determine if immune checkpoint blockade could be a potential therapeutic for AD and related dementias and whether APOE carrier status modifies benefit." (PMID 37584418, 2023). "The associations were greater amongst participants with a lower genetic risk of dementia based on APOE, but not non-APOE polygenic risk." (PMID 37605228, 2023). "For example, higher MedDiet adherence was associated with lower dementia risk in APOE ε4 carriers but not non-carriers in one study." (PMID 36915130, 2023). "Similar results were observed for the combination of APOE ɛ4 and weight change on dementia." (PMID 35921193, 2023). "We re-estimated measures of additive interaction to test whether the omission of the genetic influence of APOE-ε4 on dementia biased our mediation decomposition results." (PMID 37323925, 2023). "With the exception of visuospatial ability, the effect sizes were of similar magnitude, indicating that the APOE e4-cognition associations were not driven by a sub-group who subsequently developed dementia." (PMID 36481934, 2023). "Our previous studies showed that the elevation in cortisol concentrations is associated with MCI and dementia, independent of APOE genotypes." (PMID 37190655, 2023). "In addition, it is well known that APOE e4 heterogeneity or homogeneity bring forward the time of a dementia diagnosis in AD patients." (PMID 37131241, 2023). "Compared with non-carriers, carriers of APOE-ɛ4 with the fourth quartile of PRS had a greater risk of dementia, while the presence of the APOE-ɛ4 in individuals with the first quartile was not a significant risk factor in our cohort." (PMID 37834213, 2023). "Thus, our findings filled the gap regarding the contribution of APOE to cerebral atrophy in the transition from normal cognitive stages to dementia." (PMID 37323144, 2023). "In men, compared to participants with lowest tertile of vitamin D, those with the highest tertile of vitamin D had a lower risk of dementia in both APOE e4 non-carries (HR = 0.65, 95% CI 0.56–0.75) and APOE e4 carries (HR = 0.80, 95% CI 0.69–0.92)." (PMID 37246226, 2023). "Among the lower risk APOE group, participants in the weight loss group are 15.6% more likely to have a dementia diagnosis, independent of APOE ε4 status." (PMID 37628615, 2023). "Here we performed the largest GWAS to identify novel genetic factors affecting plasma ApoE level as well as to test if baseline plasma ApoE level affects cognitive function and incident dementia in a longitudinal cohort of the Ginkgo Evaluation of Memory (GEM) study." (PMID 37666928, 2023). "Apolipoprotein E4 (APOE4) genotype status was usually seen as an important factor for dementia." (PMID 37409011, 2023). "Plasma levels of 14 complement biomarkers were measured in 71 adults with DS and 46 controls to identify DS‐associated dysregulation; impact of apolipoprotein E (APOE) ε4 genotype, single nucleotide polymorphisms (SNPs) in CLU and CR1, and dementia on complement biomarkers was assessed." (PMID 36149090, 2023). "Type 2 diabetes per se has often been found to be associated with dementia, in particular among non-carriers of the APOE-4 allele." (PMID 37420130, 2023). "Among the additional and occasionally observed dementia risk predictors most noticeably missing from the leading cluster in this study were: (a) orthostatic hypotension, (b) REM sleep disorder, (c) sex, and (d) APOE." (PMID 37455938, 2023). "Among those with BMI loss >10%, APOE ɛ4 carriers also showed a higher risk of dementia compared with noncarriers (HR = 1.93, 95% CI 0.79–4.41, p = .129), albeit not statistically significant." (PMID 35921193, 2023). "An interaction for the APOE e4 gene between dementia severity and CHIPS was noted." (PMID 36864910, 2023). "The APOE*ε4 allele is consistently linked to abnormal Aβ aggregation and predicts longitudinal Aβ accumulation in plaque-free elderly individuals without dementia." (PMID 36937877, 2023).